TSG101 (tumor susceptibility 101)
Description:
Component of the ESCRT-I complex, a regulator of vesicular trafficking process. Binds to ubiquitinated cargo proteins and is required for the sorting of endocytic ubiquitinated cargos into multivesicular bodies (MVBs). Mediates the association between the ESCRT-0 and ESCRT-I complex. Required for completion of cytokinesis; the function requires CEP55. May be involved in cell growth and differentiation. Acts as a negative growth regulator. Involved in the budding of many viruses through an interaction with viral proteins that contain a late-budding motif P-[ST]-A-P. This interaction is essential for viral particle budding of numerous retroviruses. Required for the exosomal release of SDCBP, CD63 and syndecan. It may also play a role in the extracellular release of microvesicles that differ from the exosomes.
Synonyms: VPS23; TSG10
Tractability: Small molecule: a structure with a bound ligand is known; it has a high-quality binding pocket. Antibody: a drug acting on it is in phase 1 trials; UniProt places it where antibodies can reach, with high confidence; its Gene Ontology location is reachable by antibodies, with high confidence. PROTAC: UniProt records ubiquitination sites on it; ubiquitination databases record sites on it; its protein half-life has been measured; a small molecule that binds it is known.
Gene: Protein-coding gene on chromosome 11 (18,468,336 to 18,526,965, reverse strand). Ensembl gene ENSG00000074319.
Subcellular location: Cytoplasm; Early endosome membrane; Late endosome membrane; Cytoplasm, cytoskeleton, microtubule organizing center, centrosome; Midbody, Midbody ring; Nucleus
Subcellular location (Human Protein Atlas): Cytosol; Nucleoli; Plasma membrane
Pathways (Reactome):
Disease: Assembly and Release of Dengue Virus Virions; Budding and maturation of HIV virion; HCMV Late Events; Membrane binding and targetting of GAG proteins
Autophagy: Late endosomal microautophagy
Vesicle-mediated transport: Endosomal Sorting Complex Required For Transport (ESCRT)
Gene Ontology:
Molecular function: calcium-dependent protein binding; protein binding; protein homodimerization activity; protein-containing complex binding; ubiquitin binding; ubiquitin protein ligase binding; virion binding; DNA binding; transcription corepressor activity; ubiquitin conjugating enzyme activity
Biological process: extracellular transport; negative regulation of epidermal growth factor receptor signaling pathway; negative regulation of epidermal growth factor-activated receptor activity; positive regulation of exosomal secretion; positive regulation of viral budding via host ESCRT complex; regulation of extracellular exosome assembly; regulation of MAP kinase activity; ubiquitin-dependent protein catabolic process via the multivesicular body sorting pathway; viral budding; viral release from host cell; autophagosome maturation; endosome to lysosome transport; macroautophagy; membrane fission; multivesicular body assembly; protein transport to vacuole involved in ubiquitin-dependent protein catabolic process via the multivesicular body sorting pathway; viral budding via host ESCRT complex; exosomal secretion; negative regulation of DNA-templated transcription; positive regulation of ubiquitin-dependent endocytosis; protein transport; regulation of DNA-templated transcription
Cellular component: cytoplasm; cytosol; early endosome; early endosome membrane; endosome; ESCRT I complex; extracellular exosome; late endosome; late endosome membrane; nucleus; plasma membrane; endosome membrane; multivesicular body; centrosome; Flemming body
Genetic constraint (gnomAD): Loss-of-function variants: 17 observed, 39.16 expected, observed/expected ratio (o/e) 0.43, 90% interval 0.3 to 0.65. The upper end of that interval is the gene's LOEUF score, 0.65, which puts it in group 2 of 6, group 1 being the genes least tolerant of losing a copy. Missense variants: 349 observed, 471.67 expected, observed/expected ratio (o/e) 0.74, 90% interval 0.68 to 0.81. Synonymous variants: 169 observed, 166.25 expected, observed/expected ratio (o/e) 1.02, 90% interval 0.9 to 1.15.
Homologues: Orthologues: macaque TSG101 (100% identical), rabbit TSG101 (99% identical), guinea pig TSG101 (99% identical), dog TSG101 (98% identical), mouse Tsg101 (95% identical), rat Tsg101 (94% identical), chimpanzee TSG101 (91% identical), zebrafish tsg101a (84% identical), tropical clawed frog tsg101 (83% identical), zebrafish tsg101b (76% identical), Drosophila melanogaster TSG101 (52% identical), Caenorhabditis elegans tsg-101 (40% identical). Paralogues in human: UEVLD (29% identical).
Diseases named in the same sentence as TSG101 in open-access papers:
TSG101 is named in the same sentence as 93 diseases in open-access papers, as found by Europe PMC text mining. Sharing a sentence is not in itself a finding about the gene and the disease. The quoted sentences say what the papers report.
breast carcinoma (22 papers, 1999 to 2025). "Recurrent mutations in the gene encoding TSG101 have not been identified in human breast cancers, but elevated levels of TSG101 transcripts are associated with a more dismal prognosis for luminal-type breast cancers." (PMID 40624726, 2025). "We also show that the loss of TSG101 in connection with inactivated tumor suppressors BRCA1/2 in breast cancer cells is lethal." (PMID 36124865, 2022). "As a second line of evidence, we analyzed the dependency status of BRCA1/2‐deficient breast cancer cells to TSG101 expression in the DepMap database." (PMID 36124865, 2022). "When the human TSG101 gene was first identified, genomic mutations and alternatively spliced mRNA isoforms were detected in human breast cancer." (PMID 30759747, 2019). "Of interest, this list included TSG101, a gene with putative tumour suppressor roles and a candidate breast cancer predisposition gene." (PMID 20019873, 2009). "To gain insight into the molecular pathways that are associated with TSG101-induced mammary tumorigenesis, we compared the gene expression profiles of TSG101-induced mammary tumors with RNA sequencing data from mammary gland tissues of three FVB wild-type females." (PMID 40624726, 2025). "In 1997, TSG101 had become more widely known as a tumor suppressor when it was reported that this gene is mutated, or its expression is lost in a significant subset of sporadic breast cancers." (PMID 32075127, 2020). "It was reported that siRNA-mediated downregulation of TSG101 caused partial cell cycle arrest and reduced the colony formation capacities of prostate and breast cancer cells, and notably, it diminished the migratory activity of breast cancer cells." (PMID 30759747, 2019). "Moreover, recent studies also showed that positive TSG101 expression was associated with the clinical, pathological, and biological behaviors and with poor prognosis in breast cancer and hepatocellular carcinoma." (PMID 30675171, 2019). "Using immunohistochemistry on formalin-fixed sections of 16 human breast cancers and 16 normal breast tissues and benign hyperplasia, we found that the levels of TSG101 were significantly higher in approximately half of the invasive breast cancer cases." (PMID 40624726, 2025). "We performed RNA sequencing on ten tumor specimens to classify TSG101-overexpressing mammary carcinomas based on their intrinsic gene expression profiles." (PMID 40624726, 2025). "In contrast to the mRNA expression, we observed that the TSG101 protein expression was 2–sixfold higher in 10 of 14 breast cancer cell lines in comparison to two normal cell lines that we examined by immunoblot analysis." (PMID 40624726, 2025). "This suggested that similar to the corresponding human neoplasms, adenosquamous mammary carcinomas in TSG101-overexpressing females were typically low-grade." (PMID 40624726, 2025). "Compared to the normal mammary glands of MMTV-tTA TetO-Tsg101 double transgenic females, the expression of exogenous TSG101 was significantly higher in most mammary cancers." (PMID 40624726, 2025). "Unsupervised hierarchical clustering based on 1,723 intrinsic genes of ten TSG101-overexpressing cancers alongside 251 tissue samples representing 31 reference mammary tumor models and normal mammary glands was conducted." (PMID 40624726, 2025). "The computational analysis revealed that TSG101-overexpressing tumors are most similar to luminal-type mammary cancers that developed late in MMTV-Wnt1 (Wnt1-LateEx) transgenic females." (PMID 40624726, 2025). "A shared feature of the TSG101 and late Wnt1-induced luminal-type mammary tumors is the expression of genes that belong to the basal gene cluster (left)." (PMID 40624726, 2025). "Similar to neoplasms of the same histopathologic subtypes in humans, all TSG101-induced mammary tumors were comprised of cytokeratin 8 and 18 (CK8/18)-positive luminal epithelial cells and basal cells expressing CK5 and CK14 (upper)." (PMID 40624726, 2025).
breast carcinoma (continued). "This would explain why the reproductive status of a female is the primary determinant for the TSG101-induced formation of large mammary tumors." (PMID 40624726, 2025). "Similar to the ablation of exogenous TSG101 in mammary tumors, the conditional knockout of TSG101 led to the downregulation of the steady-state protein expression of ERBB receptors prior to cell death." (PMID 40624726, 2025). "While the hyperplastic lesions within extended mammary ducts of TSG101-overexpressing mice were similar to AMEs, the palpable mammary tumors presented as adenosquamous carcinomas, sometimes retaining features of AMEs in focal areas." (PMID 40624726, 2025). "At the molecular level, TSG101-induced mammary tumors are triple-negative and exhibit gene expression signatures of Wnt and inflammatory cytokine signaling, which are key regulators of epithelial cell fate." (PMID 40624726, 2025). "AKT1 (Gene Entrez ID 207) and TSG101 (Gene Entrez ID 7251) are the breast cancer gene markers that eDRW+ has detected for the GSE1456 and GSE1561 datasets." (PMID 34573857, 2021). "Similar to breast cancer, it has been reported that TSG101 is upregulated in human ovarian epithelial cells that express oncogenic HRAS or KRAS as well as in 70% of human ovarian carcinomas analyzed on tissue arrays." (PMID 32075127, 2020). "Using immunohistochemistry staining on a limited set of primary human breast cancers and normal breast tissues, our team observed that TSG101 is elevated in 50% of invasive breast cancers." (PMID 32075127, 2020). "Deletion of both alleles of Tsg101 in established, ERBB2-transformed mammary cancer cells causes cell death (Triplett and Wagner, unpublished)." (PMID 32075127, 2020). "In contrast to the heart-specific overexpression model, a subset of transgenic females (approximately 20%) that express exogenous TSG101 under control of the Wap gene promoter developed mammary tumors after a relatively long latency." (PMID 32075127, 2020). "Accordingly, when leptin activity was inhibited by using the full leptin receptor antagonist, the peptide LDFI, both Tsg101 expression and the amount of exosomes released by leptin-treated breast cancer cells were reduced." (PMID 31336913, 2019). "We have found a direct association between TSGΔ154-1054 expression and increased TSG101 protein in both NPC and breast cancer patients." (PMID 26811492, 2016). "In support to this model, several components of this biological process display tumour suppressor function, as demonstrated by the original identification of the endosomal protein TSG101 in human breast cancer." (PMID 26899482, 2016). "Further evidence describes Tsg101 up-regulation in tumor malignancies like breast cancer, papillary thyroid and colorectal carcinomas." (PMID 24641493, 2014). "Recent studies have localized the TSG101 gene in this region, and also demonstrated a high frequency of abnormalities of this gene in human breast cancer." (PMID 10027311, 1999). "This might explain why the expression of the TSG101 protein is significantly higher in many human breast cancer cell lines compared to untransformed epithelial cells despite similar mRNA expression levels." (PMID 40624726, 2025). "More importantly, the growth and survival of mammary carcinoma cells in tumor-bearing mice were dependent on the sustained upregulation of TSG101, suggesting that this oncoprotein might serve as a rational therapeutic target." (PMID 40624726, 2025). "Interestingly, the overexpression of TSG101 led to a significant increase in MDM2 expression in established mammary tumors (right)." (PMID 40624726, 2025). "In addition, there were several genes within the luminal gene expression subcluster that discriminated TSG101-overexpressing and late Wnt1-induced mammary cancers from typical luminal tumors that originated in MMTV-neu and MMTV-PyMT mice (right)." (PMID 40624726, 2025).
breast carcinoma (continued). "In addition to their gene expression profiles, TSG101-induced mammary cancers and Wnt1-LateEx tumors share several commonalities, such as their mixed composition of cancer cells with luminal and basal epithelial cell characteristics." (PMID 40624726, 2025). "However, a more detailed analysis of the levels of TSG101, in particular breast cancer subtypes, using quantitative methodologies is still warranted." (PMID 32075127, 2020). "For instance, downregulation of Tsg101 by small interfering RNA induced apoptosis and inhibited proliferation in MCF-7 breast cancer cells, and mammary-gland specific knockout of Tsg101 gene resulted in an impaired growth of epithelial cells as well as in an absence of mammary tumor development." (PMID 31336913, 2019). "This suggests that a post-translational mechanism could be involved in leptin mediated Tsg101 upregulation in breast cancer cells." (PMID 31336913, 2019). "The expression of these Rab family components was not modulated by leptin treatment, indicating that leptin effects on exosome release might be dependent on the induction of Tsg101 expression in breast cancer cells." (PMID 31336913, 2019). "For instance, it has been reported that cancer gene TSG101 could perturb the cell cycle pathway in breast cancer." (PMID 23579546, 2013). "It is therefore not known whether a persistently high expression of TSG101 in diverse epithelial subtypes of the mammary gland may cause an earlier onset of mammary cancer." (PMID 32075127, 2020). "Moreover, we did not observe any significant changes in the expression of proteins belonging to the Rab family of small GTPase, involved in MVB mobilization and fusion to plasma membrane, further highlighting Tsg101 as a leptin effector in breast cancer able to control exosome biogenesis." (PMID 31336913, 2019). "These evidences are in line with the role of leptin in promoting growth and invasion of breast cancer that could be additionally sustained through the induction of Tsg101 expression, since Tsg101 plays an important role in several aspects of breast tumor progression." (PMID 31336913, 2019). "Accordingly, we found in breast cancer cells that the member of the Hsp family Hsp90, which we have previously demonstrated to be a leptin target gene, physically interacts with Tsg101 in basal condition and that the amount of Tsg101 bound to Hsp90 results enriched in cells treated with leptin." (PMID 31336913, 2019). "Moreover, none of the untransformed mammary epithelial cells and breast cancer cell lines exhibited shorter TSG101 protein variants that may have originated from aberrant or alternative mRNA splice products." (PMID 40624726, 2025). "The collective findings of this study provide in vivo evidence that TSG101 possesses pro-tumorigenic properties that extend to cancer progression and maintenance, suggesting that this protein could be a rational molecular target to prevent and treat a subset of mammary tumors." (PMID 40624726, 2025). "Similar to the reported posttranslational downregulation of the ESCRT-1 binding partner VPS28 in siRNA-mediated TSG101 knockdown cell lines, we observed a concomitant upregulation of VPS28 in mammary tumors with high overexpression of TSG101." (PMID 40624726, 2025). "Western blot results showed that the exosome markers TSG101 and CD9 were expressed in exosomes derived from breast cancer cells." (PMID 39198393, 2024). "We also demonstrate a co‐dependency of TSG101 and BRCA1/2 for the survival of breast cancer cells, similar to the synthetic lethality observed for PARP inhibitor olaparib and BRCA1/2 deficiency." (PMID 36124865, 2022). "Western blot analysis show that EpCAM-positive breast cancer exosomes express AnxA2 and exosomal markers CD9, TSG101, and flotillin-1." (PMID 31992335, 2020). "In follow-up studies, we found a direct correlation between TSGΔ154-1054 expression and abundance of TSG101 protein in both NPC and breast cancer." (PMID 26811492, 2016).
breast carcinoma (continued). "The absence of FOXA1 staining in these carcinoma cells supported the finding that the growth of the triple-negative TSG101-induced mammary tumor cells was likely not controlled by steroid hormones." (PMID 40624726, 2025). "Similar to human cancer cell lines, the lack of TSG101 prevented the initiation of ERBB2/neu-induced mammary cancer." (PMID 40624726, 2025). "In relation to our previous study on canine mammary tumor cell-derived EVs, while integrin-beta and TSG101 were not tested as EV markers, CD9 was present in both UC and SEC EVs." (PMID 37958059, 2023). "However, Tsg101 was also found to support proliferation: Deletion of Tsg101 in mammary epithelia (using MMTV-Cre) did not result in breast cancer development in mice but impaired proliferation of the Tsg101 deficient cells in vitro." (PMID 24641493, 2014). "The pro-proliferative role of Tsg101 itself appears to extend to tumor cells as a reduction of Tsg101 protein by siRNA had a negative impact on tumor cell growth and compromised the MAPK/ERK signal pathway in breast cancer cells." (PMID 24641493, 2014). "Besides cell invasion, we found that TSG101 depletion did not affect cell growth or cell migration of HT1080 or HeLaS3 cells, although it was reported that TSG101 depletion inhibits cell growth and cell migration of prostate cancer PC3, breast cancer MDA-MB-231, and breast cancer MCF-7 cells." (PMID 26608825, 2015).